DNM1P35 (dynamin 1 pseudogene 35)
Synonyms: DNM1DN8-2; formerly DNM1DN8@
Gene: Long non-coding RNA gene on chromosome 15 (75,727,670 to 75,739,045, reverse strand). Ensembl gene ENSG00000246877.
Diseases named in the same sentence as DNM1P35 in open-access papers:
DNM1P35 is named in the same sentence as 2 diseases in open-access papers, as found by Europe PMC text mining. Sharing a sentence is not in itself a finding about the gene and the disease. The quoted sentences say what the papers report.
kidney cancer (1 paper, 2024). Primary or metastatic malignant neoplasm involving the kidney. "Another example is the lncRNA DNM1P35, which serves as a novel prognostic factor for kidney cancer." (PMID 39118043, 2024).
cancer (1 paper, 2020). A tumor composed of atypical neoplastic, often pleomorphic cells that invade other tissues. "As a conclusion, our robust network-based framework has derived 31 AS-related lncRNAs that not only validates known cancer-associated cases MALAT1 and HOXA11-AS, but also reveals new players such as DNM1P35 and DLX6-AS1with potential functional implications." (PMID 32760422, 2020).